CDC20 (cell division cycle 20)
Diseases named in the same sentence as CDC20 in open-access papers (continued):
Sharing a sentence is not in itself a finding about the gene and the disease.
cancer (continued). "Nevertheless, inhibition of APC/CCdc20 activity or induction of Cdc20 degradation have already been listed as alternative therapeutic strategies to control cancer." (PMID 39412391, 2024). "The observed anti-cancer effect of inhibiting CDC20 through gene silencing, or chemically through APCIN or TAME, can be interpreted in several ways." (PMID 38730707, 2024). "In the context of NSCLC, combining CDK inhibition with the resulting impact on CDC20 can be a strategic approach to limit the proliferation of cancer cells, potentially enhancing treatment effectiveness." (PMID 39457373, 2024). "A recent series of papers found that APC substrate mRNAs, including HURP and CDC20, are elevated in multiple cancers, and are now recognized as a hub or signature gene set predictive of poor prognosis cancer (a subset of references are included here;)." (PMID 38730707, 2024). "The expression of CDC20 in the other cancer types was also addressed using the information available on various databases." (PMID 39061186, 2024). "There is mounting evidence of the druggability of human Cdc20 to interfere with APC/C functions in cancer cells, where the attention has been centred on the development of compounds that bind the Cdc20 D-box located in the C-terminal of the WD40 domain." (PMID 39595615, 2024). "Our study found that CDC20 mRNA expression levels were significantly overexpressed in most human cancers, as documented in the UALCAN, TCGA, and TIMER2." (PMID 39061186, 2024). "CDC20 is frequently overexpressed in various malignant tumors and exerts its main function by promoting resistance to both chemotherapy and radiation." (PMID 39125953, 2024). "In this study, we aim to delve deeper into the mechanisms by which CDC20 regulates the resistance of cancer cells to radiotherapy and chemotherapy." (PMID 39125953, 2024). "Abnormal expression of CDC20 leads to mitotic defects, which play a significant role in cancer development." (PMID 39061186, 2024). "First, the expression levels of CDC20 after radiation were analyzed in eight cell lines from different cancer types, including KYSE70, KYSE200, KYSE450, H1299, TE10, HCT116, MDA-MB-231, and BT549." (PMID 39125953, 2024). "Given the oncogenic role for CDC20-APC/C in tumor progression as well as its role in drug resistance, the inhibition of CDC20-APC/C activity or the induced degradation of CDC20 are emerging as alternative therapeutic strategies to control cancer." (PMID 38523261, 2024). "Because human ERKs are homologs of fission yeast Pmk1, the finding in this study supports a notion that very likely human MAPKs also negatively regulates APC/C through Cdc20 phosphorylation and the altered levels of Cdc20 in cancers are MAPK relevant." (PMID 39412391, 2024). "CDC20 is highly expressed in several tumor types, making it a potential therapeutic target for cancer." (PMID 39902297, 2024). "Inactivation of Cdc20 sensitized cancer cells to treatment with the ER stress inducer in a TPD52‐dependent manner." (PMID 39401430, 2024). "In normal cells, the CDC20 protein is responsible for complex activities during mitosis, and it was shown to be overexpressed in various types of human cancer." (PMID 38612439, 2024). "APC-targeted proteins, such as CDC20, Securin, HURP, FOXM1, PLK1, and the Aurora kinases, accumulate in multiple unrelated cancer types and are generally associated with more aggressive disease and worse clinical outcomes." (PMID 38730707, 2024). "Cdc20 is overexpressed in various cancer stem cells and malignant tumors, and its inhibition has been proposed as a targeted therapy for cancer patients." (PMID 37110415, 2023). "TCGA statistics show that the Cdc20 gene is overexpressed in a variety of human tumor tissues, including breast cancer, cervical cancer, colorectal cancer, liver cancer, and other cancer tissues." (PMID 37259447, 2023).
cancer (continued). "When we analysed the cancer-specific genes like Cdc20, Hmmr, Tpx2, Cenpf, Birc5, Ube2c, Foxm1,Pold4, Nup210, Cenpm and Orc1, these pro-carcinogenic genes found to be over expressed in the disease control group." (PMID 36650455, 2023). "CDC20 regulates apoptosis of cancer cells mainly by interacting with related proteins and the Wnt/β-catenin signaling pathway." (PMID 37682144, 2023). "Preclinical exploration have shown that specific CDC20 inhibitors, including proTAME and Apcin, are effective against multiple types of malignant tumors, resulting in mitotic arrest and apoptosis and synergizing with clinically-relevant drugs." (PMID 37528490, 2023). "CDC20 was confirmed to be involved in the infiltration of cancer-related fibroblasts and myelogenous suppressor cells." (PMID 36909154, 2023). "Studies have shown that Frondoside A can down-regulate CDC20 gene expression, which inhibits the proliferation and migration of cancer cells and promotes cycle arrest and cell apoptosis." (PMID 38144520, 2023). "Multiple studies have demonstrated that CDC20 can regulate the proliferation and progression of cancers through signaling pathways, interactions with related protein factors, and angiogenesis." (PMID 37682144, 2023). "CDC2 has oncogenic properties and also regulates anticancer drug responses, and is considered an emerging target for cancer therapeutic intervention Additionally, CDC20 was reported to be related to immune infiltration in cancer." (PMID 38044951, 2023). "In CRPC, the abnormal upregulation of CDC20 leads to the failure of mitotic arrest and progression through the cell cycle and division of cancer cells with aneuploidy, thus increasing oncogenic proliferation and driving disease progression." (PMID 36937454, 2023). "CDC20 inhibitor Apcin has been reported to inhibit cancer cell proliferation by competitively inhibiting anaphase-promoting complex/Cyclosome (APC/C)-dependent ubiquitination." (PMID 36911196, 2023). "To date, a lot of APC substrates involved in cell cycle regulation have been demonstrated to be overexpressed in several cancer types, including CDC20, the Aurora A and B kinases (AURKA and AURKB, respectively) and Forkhead box M1 (FOXM1)." (PMID 37447165, 2023). "Inhibition of CDC20 has been demonstrated in multiple cancer cell models including PCa by the compound Apcin." (PMID 36937454, 2023). "We anticipate that CDC20 will be a promising and effective biomarker and therapeutic target for the treatment of human cancer." (PMID 37682144, 2023). "CDC20 not only regulates the proliferation of cancer cells, but also promotes invasion and metastasis." (PMID 37682144, 2023). "CDC20 not only regulates cancer cell proliferation and progression but also promotes resistance to chemotherapy and radiotherapy." (PMID 37682144, 2023). "According to the UALCAN database, the mRNA expression of CDC20 was identified to be significantly correlated with the tumor grade and the cancer stage of HCC." (PMID 35622386, 2022). "A correlation between higher Cdc20 expression and poorer prognosis has been demonstrated in various malignant tumors such as breast or non-small cell lung cancer (NSCLC)." (PMID 35832196, 2022). "The possible correlation between the elevated CDC20 and mitotic slippage was observed in different types of cancer cells." (PMID 35954396, 2022). "The HBx combo mutation C1653T+T1674G+A1762T/G1764A promotes carcinogenesis via upregulating the expression of PAI1 and CDC20 and inducing cancer-promoting inflammation." (PMID 35223517, 2022). "Despite conditions that activate the SAC, CDC20-APC/C is activated upon mitotic slippage of cancer cells to G1 phase cells." (PMID 35954396, 2022). "Recent Cancer Genome Atlas (TCGA) and human specimen-orientated pathological cohort studies have demonstrated a strong correlation between the uncontrolled accumulation of CDC20 with poor prognosis of cancers." (PMID 35954396, 2022).
cancer (continued). "Our study is the first to demonstrate this relationship between CDC20 and Bim in primary human cancer cells." (PMID 35737702, 2022). "Early studies showed that CCT activity is necessary for cancer cell proliferation due to the need for the functional forms of cytoskeletal proteins as well as cell cycle regulators like Cdc20 and Cdh1." (PMID 35602608, 2022). "When combining the top 100 co-expressed genes for each cancer type, some genes occurred more than once, e.g. AURKB (encoding for Aurora kinase B) and CDC20 (encoding for Cell division cycle 20) were the most frequent among the combined list of 3200 genes." (PMID 35331169, 2022). "We examined the relationship between gene expression of CDC20 and UBE2C and 24 immunoinhibitors among pan cancer to evaluate their clinical significance in association with immune moderation." (PMID 36385010, 2022). "recently showed that cell cycle signaling was associated with high cancer stemness of EAC, such as E2F3, CHEK1, CDC20, SMC3, and TFDP1." (PMID 35785171, 2022). "The expression levels of some interactors (BUB1, CCNA2, CCNB1, CDK1, MAD2L1, and PLK1) were positively correlated with CDC20 in cancer cells." (PMID 35490245, 2022). "In the present study, we find that loss of Cdc20-APC/C–mediated signaling has different functional outcomes in normal and cancer cells." (PMID 35988650, 2022). "Future clinical studies and chemical modifications will enhance the application of CDC20 inhibitors in anti-cancer treatment." (PMID 35954396, 2022). "CD5L, LCAT and CDC20 were shown to be significantly correlated with immune/stroma cell infiltrations, immunoregulators and 31 anti-cancer drug sensitivities in HCC." (PMID 36494696, 2022). "CDC20 is well-characterized as an oncogene and was shown to be highly expressed in several human cancers." (PMID 35954396, 2022). "Our findings shared novel insights into the association between CDC20 and infection-related HCC on the bases of various studies about CDC20 and cancers." (PMID 35622386, 2022). "In this study, we also explored the potential roles of CD5L, LCAT, and CDC20 in HCC therapy and found their associations with anti-cancer drug sensitivities in HCC cell lines." (PMID 36494696, 2022). "Knockdown of CDC20 in different cancer cell lines with high baseline CDC20 expression resulted in upregulation of Bim and increased sensitivity to radiation and a number of chemotherapeutics." (PMID 35737702, 2022). "LncRNA DEPDC-AS1 as well as CCNB1 and CDC20 had significantly higher expressions in carcinoma of urinary bladder tissues compared to normal paracancerous tissues." (PMID 35280820, 2022). "The expression of lncRNA DEPDC-AS1, CCNB1 and CDC20 in carcinoma of urinary bladder cell line was determined by qRT-PCR analysis." (PMID 35280820, 2022). "It has been reported that overexpression of CDC20 promoted cancer progression, whereas its knockdown suppressed cancer." (PMID 33851100, 2021). "Studies have found that after CDC20 is inhibited, the growth of cancer cells will be inhibited, G2/M phase arrest and apoptosis." (PMID 34512169, 2021). "By analyzing the abundance of Cdc20 and its substrates, CDC20 is probably functionally active in the CDC20 high-expression cancer types." (PMID 34527589, 2021). "Overall, among 33 cancer types in the TCGA dataset, the high expression of CDC20 was correlated with poor prognosis in 10 cancer types, which further supports its oncogenic role in tumor progression." (PMID 34527589, 2021). "Among 33 cancer types in the TCGA dataset, the high expression of CDC20 was correlated with poor prognosis in 10 cancer types, which further supports its oncogenic role in tumor progression." (PMID 34527589, 2021). "The high expression of CDC20 was negatively correlated with the overall survival (OS) in multiple cancer types, especially ACC, KIRC, KIRP, LGG, LIHC, LUAD, MESO, and SKCM." (PMID 34527589, 2021).
cancer (continued). "For most cancer types, the CDC20 expression was positively correlated with the infiltration of CAFs and MDSCs, while the correlation was significantly negative in a small group of cancer including BRCA." (PMID 34527589, 2021). "In cancer cells, HSF1 is phosphorylated by polo-like kinase 1 (PLK1) at serine 216, causing it to sequester Cdc20." (PMID 34922589, 2021). "Next, we aim to investigate the mutually molecular functions of CDC20 in multiple tumor genesis at the pan-cancer level." (PMID 34527589, 2021). "Recent studies have shown that CDC20 also plays an important role in carcinogenesis and cancer progression and has the potential to be a promising therapeutic target." (PMID 34753395, 2021). "We systematically compared the mRNA expression of CDC20 between cancer and normal tissues in various cancers based on TCGA datasets." (PMID 33851100, 2021). "CDC20 was upregulated in many types of cancers including HCC according to the GEO database through UALCAN and GEPIA." (PMID 34512169, 2021). "Together, these results demonstrate that the expression of CDC20 significantly increased and correlated with increased clinical stages in multiple cancer types." (PMID 34527589, 2021). "Genetic amplification of CDC20 suggests an oncogenic driving function of CDC20 in cancer progression." (PMID 33851100, 2021). "Together, these results indicated that Cdc20 is functionally active in the CDC20 high-expression cancer types." (PMID 34527589, 2021). "The CNV amplification and mRNA up-regulation of CDC20 in cancer versus normal is one rationale for us to further investigate the function of these CDC20 promoter noncoding hotspot mutations." (PMID 33851100, 2021). "Previous studies reported that CDC20 is involved in the occurrence and progression of a variety of malignant tumors." (PMID 34512169, 2021). "Among 33 cancer subtypes in the TCGA dataset, the high expression of CDC20 was correlated with poor prognosis in 10 cancer types." (PMID 34527589, 2021). "The abundance of total Cdc20 protein was significantly elevated in BRCA, LUAD, UCEC, in which the mRNA expression of CDC20 was also increased in cancer tissues." (PMID 34527589, 2021). "If the Cdc20 was functionally active in specific cancer, the protein abundance of its classic substrates should be degraded significantly and down-regulated in RPPA analysis." (PMID 34527589, 2021). "Herein, to further explore the functional activity in cancer biology, we analyze the abundance of Cdc20 and its substrates at the pan-cancer level." (PMID 34527589, 2021). "Next, we investigated the correlation of CDC20 mRNA expression with the prognosis of patients with different cancer types in TCGA." (PMID 34527589, 2021). "Cdc25, Cdc20, and Plk1 are well-known direct targets for inhibitors that are used to induce a cell cycle arrest in cancer cells and tumor regression." (PMID 34887439, 2021). "Next, to verify the overexpression pattern of CDC20 in indicated cancer types, the GTEx dataset was included and served as control groups with the TCGA normal datasets." (PMID 34527589, 2021). "Firstly, we explore the mRNA expression pattern of the CDC20 gene in various cancer and normal tissues of 33 cancer types or subtypes from the TCGA database using the TIMER 2.0 approach and R, respectively." (PMID 34527589, 2021). "More importantly, the CDC20 mRNA levels were dramatically and positively correlated with the infiltration of MDSCs, which indicated the immune suppression role of CDC20 in cancer patients." (PMID 34527589, 2021).
cancer (continued). "While CDC20 was highly expressed in carcinoma cells, proliferation cells, T cells, tissue monocytes 1(TM1), and pericytes." (PMID 34726341, 2021). "In summary, our results indicate that targeting CDC20 is a promising strategy to improve cancer radiotherapy." (PMID 32932732, 2020). "Since Cdc20 is an oncogenic cofactor in the APC/C complex, many efforts have been made to find Cdc20 inhibitors to anti-cancer." (PMID 33643919, 2020). "HSF1 functions in cancer by inhibiting the interaction of CDC20 with CDC27 and blocking APC activation." (PMID 32805721, 2020). "Meanwhile, CDK1, CCNA2, CCNB2, BUB1B and CDC20 were classified as cancer-related genes, and RRM2 was an FDA approved drug target." (PMID 33083112, 2020). "Many APC substrates have been observed overexpressed in multiple cancer types, such as CDC20, the Aurora A and B kinases, and Forkhead box M1 (FOXM1), suggesting APC activity is important for cell health." (PMID 32805721, 2020). "First, the expression of CDC20 gene in 20 types of cancer was measured and compared with normal tissues using the Oncomine online database." (PMID 32285914, 2020). "Accordingly, a significant chromosomal disorder was observed in CDC20-silenced cells that was very similar to early cancer phenotypes." (PMID 32322666, 2020). "The role of CDC20 as an oncogene has been increasingly recognized and widely reported in a variety of human cancers." (PMID 32932732, 2020). "CDC20 is an oncogene whose overexpression has been observed in numerous cancers and which plays a pivotal role in mitotic progression." (PMID 32219041, 2020). "High expression levels of CDC20 have been reported to be correlated with poor prognosis in a variety of cancers." (PMID 31987036, 2020). "Unfortunately, only CDC20 showed a significant P-value in both databases and was regarded as a cancer-promoting gene which can be further explored as a prognostic biomarker or therapeutic target for BC." (PMID 32677673, 2020). "It has been observed that the APC activator and eventual substrate, CDC20, accumulates in many types of cancer cells in vitro and in vivo." (PMID 32805721, 2020). "CDC20 has been proved to be highly expressed in a variety of malignant tumours and is related to tumorigenesis and progression." (PMID 32458533, 2020). "The high expression of CDC20 in many kinds of malignant tumours has been reported, and it is related to the occurrence and development of tumours." (PMID 32458533, 2020). "We propose CDC20 as a prognostic marker for LIHC and KIRC, and a diagnostic marker for more than nine types of cancer." (PMID 32489468, 2020). "As a key component of the spindle assembly checkpoint, CDC20 has been reported in various malignant tumors and exhibits an important role in carcinogenesis and progression." (PMID 32043523, 2020). "In order to better understand the role of CDC20 in cancer, we obtained RNA-Seq-based CDC20 expression levels in 33 human cancers from The Cancer Genome Atlas (TCGA) rich dataset." (PMID 32932732, 2020). "Taken together, CDC20 is often over-expressed in a majority of human cancers, supporting its oncogenic role in promoting tumorigenesis, and thus CDC20 is a legitimate target of drug development for the treatment of human malignancies." (PMID 33285689, 2020). "The induction of various kinds of DNA damage by CDC20 silencing dramatically increased the resistance of normal cell lines to acid-stress-induced cell death, transforming normal cells to malignant tumor-like cells." (PMID 32322666, 2020). "Targeting CDC20 is a better cancer therapeutic strategy, because knocking down CDC20 can lead to mitotic arrest and cell death, and can effectively kill apoptosis-resistant cancer cells." (PMID 32932732, 2020).